MCAM (melanoma cell adhesion molecule)
Diseases named in the same sentence as MCAM in open-access papers (continued):
Sharing a sentence is not in itself a finding about the gene and the disease.
Ewing sarcoma (4 papers, 2019 to 2025). A small round cell tumor that lacks morphologic, immunohistochemical, and electron microscopic evidence of neuroectodermal differentiation. "Melanoma cell adhesion molecule (MCAM) is a relevant target, expressed on Ewing sarcoma (ES) and associated with metastasis." (PMID 40519903, 2025). "Our previous studies identified a new regulatory axis with growth and metastasis promotional properties, involving KDM3A, Ets1 and MCAM, in Ewing Sarcoma." (PMID 32577157, 2020). "This shared group included the transcription factor Ets1 and the cell surface protein MCAM, which our previous studies defined as part of a novel, disease-promotional axis in Ewing Sarcoma." (PMID 32577157, 2020). "In summary, we show that the KDM3A/Ets1/MCAM molecular axis, which we have previously demonstrated to manifest tumor and metastasis promotional properties in Ewing Sarcoma, also plays potent disease-promoting roles in both FN-RMS and FP-RMS." (PMID 32577157, 2020). "In mechanistic studies, we demonstrate that both RMS subtypes utilize a KDM3A/Ets1/MCAM disease-promoting axis recently discovered in Ewing Sarcoma, another aggressive pediatric cancer of distinct cellular and molecular origin." (PMID 32577157, 2020). "Inspection of individual genes of interest revealed that KDM5A and PHF2 each positively control the expression of Ets1 and MCAM, genes belonging to a metastasis-promoting pathway recently identified in Ewing sarcoma by our group, and negatively regulated by EWS/Fli1." (PMID 33196691, 2020). "We have previously identified MCAM as one such druggable target in Ewing sarcoma." (PMID 33196691, 2020). "Our previous studies showed that Ets1 directly controls MCAM expression in Ewing Sarcoma." (PMID 32577157, 2020). "This gene group includes MCAM and TNC, both recently established metastasis-promoting factors in Ewing sarcoma." (PMID 33196691, 2020). "Our previous studies in Ewing Sarcoma showed that KDM3A positively controls the expression of Ets1, and that KDM3A and Ets1 both control expression of MCAM." (PMID 32577157, 2020). "We noted Ets1 expression to be dramatically higher in RMS cell lines relative to Ewing Sarcoma A673 cells, in which we had originally identified Ets1 as an important component of the KDM3A/Ets1/MCAM disease-promoting axis." (PMID 32577157, 2020). "Specifically, we showed that, in Ewing Sarcoma, an aggressive pediatric cancer of bone and soft tissue, KDM3A acts as both a tumor promoter, and, through its downstream-induced gene MCAM, a promoter of metastasis." (PMID 32577157, 2020). "Our studies provide evidence that, in Ewing sarcoma, KDM5A activates expression of L1CAM (and MCAM) via a demethylase-independent mechanism." (PMID 33196691, 2020). "KDM3A and MCAM each present potential new therapeutic targets in both subtypes of RMS, similar to our previous findings in Ewing Sarcoma." (PMID 32577157, 2020). "However, our prior studies in Ewing Sarcoma also demonstrated KDM3A localization to the Ets1 and MCAM promoter regions, while our current analogous studies in FP-RMS did not." (PMID 32577157, 2020). "Our studies in Ewing Sarcoma and FP-RMS identify Ets1 as a direct regulator of MCAM expression." (PMID 32577157, 2020). "MCAM has previously been identified as a prevalently overexpressed cell surface protein in pediatric cancers, and our own prior studies demonstrated it to be an important mediator of KDM3A effects in Ewing Sarcoma." (PMID 32577157, 2020). "Thus, in contrast to our previous findings in Ewing Sarcoma, KDM3A does not appear to control Ets1 and MCAM expression via direct association with proximal regulatory elements in FP-RMS." (PMID 32577157, 2020).
neuroblastoma (4 papers, 2017 to 2025). Neuroblastoma (NB) is the most common solid, extracranial childhood tumor. "CAR-expressing natural killer (NK) cells targeting MCAM were characterized by significantly enhanced cytotoxic activity against MCAM+ neuroblastoma cells in vitro." (PMID 41388158, 2025). "In immunodeficient mice with primary neuroblastoma xenografts, anti-MCAM antibody therapy reduced tumor progression." (PMID 41388158, 2025). "Moreover, anti-MCAM-CAR-NK cell injection significantly decreased tumor growth and prolonged animal survival in a neuroblastoma xenograft mouse model." (PMID 41388158, 2025).
psoriasis (4 papers, 2020 to 2026). An autoimmune condition characterized by red, well-delineated plaques with silvery scales that are usually on the extensor surfaces and scalp. "Clinical trials implementing anti-MCAM antibodies in psoriasis patients have reported limited success, however, leukocyte recruitment to the brain in MS patients might still be efficiently constrained by anti-MCAM antibody treatment." (PMID 33381120, 2020).
pulmonary fibrosis (4 papers, 2019 to 2025). Chronic progressive interstitial lung disorder characterized by the replacement of the lung tissue by connective tissue, leading to progressive dyspnea, respiratory failure, or right heart failure. "To this end, we analyzed the proliferation dynamics of lineage-negative (CD45–, CD31–, EPCAM–, MCAM–) lung fibroblasts in 2 in vivo models of lung fibrosis." (PMID 40875468, 2025).
small cell lung carcinoma (4 papers, 2017 to 2025). Small cell lung cancer (SCLC) is a highly aggressive malignant neoplasm, accounting for 10-15% of lung cancer cases, characterized byrapid growth, and early metastasis. "MCAM was strikingly elevated in small cell lung cancer with chemoresistance, and the suppression of MCAM largely repressed cancer cell proliferation and drug resistance." (PMID 36340580, 2022).
colorectal tumors (3 papers, 2021 to 2023). "In addition, prominent down regulation of MCAM fucosylation was detected in colorectal tumor tissues of Fut2△IEC mice." (PMID 36739428, 2023). "More colorectal tumors were detected in Fut2△IEC mice than in control mice, and significant downregulation of melanoma cell adhesion molecule (MCAM) fucosylation was detected in the colorectal tumor tissues of Fut2△IEC mice." (PMID 36739428, 2023).
diabetic nephropathy (3 papers, 2020 to 2025). "Mouse studies suggested that, by directly binding to MCAM, Wnt5a-induced noncanonical signaling was a contributing mechanism for renal tubular inflammation in diabetic nephropathy." (PMID 41388158, 2025).
experimental autoimmune encephalomyelitis (3 papers, 2015 to 2024). An autoimmune demyelinating disease of the central nervous system that is produced experimentally in animals by the injection of homogenized brain or spinal cord in Freund's adjuvant. "The upregulation of MCAM in brain endothelial cells recruits pathogenic Th1 and Th17 CD4+ T lymphocytes expressing MCAM from circulation during neuroinflammation in experimental autoimmune encephalomyelitis (EAE) and autopsied brain samples in MS." (PMID 39408955, 2024).
malignant mesothelioma (3 papers, 2020 to 2025). A malignant neoplasm of the pleura or peritoneum, arising from mesothelial cells. "Another study has highlighted the potential of MCAM-targeted radioimmunotherapy in malignant mesothelioma by using CD146-targeting antibody OI-3 coupled with 212Pb (212Pb-TCMC-OI-3)." (PMID 40332051, 2025).
psoriatic arthritis (3 papers, 2015 to 2025). Joint inflammation associated with psoriasis. "Thus, MCAM plays a critical role in the pathogenesis of psoriatic arthritis by promoting the recruitment and activation of IL-17-producing T cells." (PMID 41388158, 2025). "This suggests that MCAM+ T cells are a key source of IL-17 in psoriatic arthritis." (PMID 41388158, 2025).
rhabdomyosarcoma (3 papers, 2020 to 2025). A rare aggressive malignant mesenchymal neoplasm arising from skeletal muscle. "In rhabdomyosarcoma (RMS), the KDM3A/Ets1/MCAM axis has been identified as a key pathway, in which KDM3A promotes the expression of MCAM, contributing to tumor growth and metastasis." (PMID 41388158, 2025).
Autoimmunity (2 papers, 2018 to 2020). The occurrence of an immune reaction against the organism's own cells or tissues. "Th17 autoreactive T cells express very high levels of MCAM and antibody-mediated blockade of MCAM reduces CNS autoimmunity." (PMID 29411111, 2018). "Other studies indicated that the transmigration of CD4+ and CD8+ T cells across the CNS autoimmunity could be controlled through additional cell adhesion molecules such as melanoma cell adhesion molecule (MCAM) and activated leukocyte cell adhesion molecule (ALCAM)." (PMID 33208141, 2020). "Additional cell adhesion molecules such as activated leukocyte cell adhesion molecule (ALCAM) and melanoma cell adhesion molecule (MCAM) also control transmigration of the CD4+ and CD8+ T cells across the BBB and CNS autoimmunity." (PMID 29411111, 2018).
chronic obstructive pulmonary disease (2 papers, 2014 to 2025). A chronic and progressive lung disorder characterized by the loss of elasticity of the bronchial tree and the air sacs, destruction of the air sacs wall, thickening of the bronchial wall, and mucous accumulation in the bronchial tree. "Furthermore, MCAM upregulation was observed not only during renal disjunctions but also in primary bronchial epithelial cells of patients with chronic obstructive pulmonary disease, suggesting that it is involved in the pathophysiology of this disease." (PMID 41388158, 2025).
gynecologic cancer (2 papers, 2013 to 2020). "Despite limited evidence, RhoB and RhoC as well as other Rho GTPase associated interactions, including melanoma cell adhesion molecule (MCAM) or regulator of chromosome condensation 2 (RCC2), represent biomarkers with potential in gynecologic cancer therapy." (PMID 32443784, 2020).
ischemia (2 papers, 2021 to 2024). A hypoperfusion of the BLOOD through an organ or tissue caused by a PATHOLOGIC CONSTRICTION or obstruction of its BLOOD VESSELS, or an absence of BLOOD CIRCULATION. "In a hindleg ischemia model, the highest numbers of macrophages were detected between 1 and 2 weeks after an irradiation, which is in accordance to the upregulated MCAM expression on lung tissue cells 2 weeks after an in vivo irradiation of the lung." (PMID 39518030, 2024).
Pleural effusion (2 papers, 2017 to 2021). The presence of an excessive amount of fluid in the pleural cavity. "Expression of MCAM in cytological smears of pleural effusions of MPM patients has been suggested as a novel marker to discriminate between malignant and reactive mesothelium." (PMID 28577209, 2017).
uveal melanoma (2 papers, 2022 to 2025). A melanoma derived from melanocytes of the uveal tract. "Supporting this mechanism, data from uveal melanoma cell lines demonstrated colocalization of galectin-3 with MCAM on the cell surface, as well as a dose-dependent increase in AKT phosphorylation following exposure to exogenous galectin-3." (PMID 41388158, 2025). "This antiangiogenic effect is also relevant in uveal melanoma, where targeting MCAM downregulates VEGFR/AKT/p38/NF-κB and FAK/VE-cadherin pathways." (PMID 41388158, 2025). "In the examined samples of malignant uveal melanoma with liver metastases, tumor cells exhibited a strong and distinct overexpression of MCAM." (PMID 41388158, 2025). "Using anti-MCAM antibody AA98 induced impaired tube formation and migration of primary human retinal microvascular endothelial cells and tube-like structure formation of uveal melanoma cells." (PMID 41388158, 2025).
abdominal aortic aneurysm (1 paper, 2023). Enlargement and ballooning of the vessel that supplies arterial blood to the abdomen, pelvis and legs. "The expression of melanoma cell adhesion molecule (MCAM) is increased in abdominal aortic aneurysms." (PMID 36959563, 2023).
benign ovarian tumours (1 paper, 2012). "Our research has shown that normal ovarian surface epithelial cells do not express MCAM and that the MCAM-positive tumour ratio is very low in benign ovarian tumours." (PMID 22610942, 2012).
brain inflammation (1 paper, 2024). "MCAM has previously been described as a cell-adhesion molecule contributing to brain inflammation by facilitating pathogenic T cell extravasation into the CNS52–54 and here, we identify a putative regenerative function of MCAM expressed by Treg." (PMID 38467607, 2024).
carcinoids (1 paper, 2019). "MCAM methylation levels were found to be significantly higher in lung typical carcinoids tumors and were proposed as a useful new molecular biomarker in this tumor type." (PMID 31126053, 2019).
cyst (1 paper, 2017). A sac-like closed membranous structure that may be empty or contain fluid or amorphous material. "In contrast, MCAM-shRNA knockdown produced obvious defects in luminal biogenesis, with misshapen lumens and disorganized F-actin (an apical marker for cyst lumens) distribution observed in approximately 83% of cysts." (PMID 28589943, 2017).
Hyponatremia (1 paper, 2020). An abnormally decreased sodium concentration in the blood. "Natriuretic peptides, hyponatremia, C-reactive protein, melanoma cell adhesion molecule (MCAM), procalcitonin, haemoglobin level, or red blood cell distribution width (RDW) are among the most available ones." (PMID 33082887, 2020).
metastasis (1 paper, 2022). The spread or migration of cancer cells from one part of the body (where they first appeared) to another. "Our analysis was limited to four genes, ASPN, POSTN, SPARCL1, and MCAM, which we determined as potential markers of stromal activation in a xenograft model of PC bone metastasis." (PMID 36185585, 2022).
SAPHO syndrome (1 paper, 2019). SAPHO syndrome (acronym for Synovitis, Acne, Pustulosis, Hyperostosis and Osteitis) is an auto-inflammatory disease, mainly characterized by the association of neutrophilic cutaneous involvement and chronic osteomyelitis. "Components of laminin (LAMA4, LAMB1 and LAMC1) and MCAM also help cell adhesion and slow-rolling of neutrophils, the up-regulation of whom indicated excessive neutrophil activation and migration in SAPHO syndrome." (PMID 31395074, 2019).
T cell lymphoma (1 paper, 2012). "Initially, we selected the MOLT4 cell line (T cell lymphoma) for these studies, confirming the high level hMCAM expression reported in the literature (FACS detection with anti-MCAM more than 10-fold above isotype control, data not shown)." (PMID 22792325, 2012).
tumor (304 papers, 2005 to 2026). "Paradoxically, increased MCAM gene expression in tumor tissue was also associated with reduced patient survival (rev." (PMID 41388158, 2025). "Elevated levels of soluble MCAM have been linked to poor outcomes in various malignancies and can influence tumor microenvironments." (PMID 41388158, 2025). "The expression of MCAM in BLCA was associated with tumor purity (r = − 0.302), CD8 + T cells (r = 0.218), CD4 + T cells (r = 0.111), macrophages (r = 0.352), neutrophils (r = 0.183), and dendritic cells (r = 0.183)." (PMID 41407823, 2025). "Another study also demonstrated that MCAM deficiency in human CRC cells significantly promotes tumor progression, further confirming its tumor-suppressive roles in CRC." (PMID 36739428, 2023). "Paradoxically, increased MCAM gene expression in tumour tissue was associated with reduced survival." (PMID 37138793, 2023). "In the same tumor context, a Chinese study described a positive Notch1 association with the expression of the melanoma cell adhesion molecule (MCAM), an EMT activator protein." (PMID 35582386, 2021). "Another possibility is the direct local tumor targeting, either using siRNA molecules against MCAM or plasmid DNA encoding shRNA against MCAM." (PMID 32204304, 2020). "In the current study, we explore the potential of the combined treatment utilizing the irradiation of tumors with local GET with plasmid DNA-encoding shRNA against MCAM in two radioresistant tumor models." (PMID 32204304, 2020). "Melanoma cell adhesion molecule (MCAM) is a cell adhesion molecule that is abnormally expressed in a variety of tumours and is closely associated with tumour metastasis." (PMID 22610942, 2012). "Linked with tumor cell adhesion and metastasis, MCAM seemed a possible candidate to augment the tissue-infiltrative potential among T cells." (PMID 22792325, 2012). "In addition to the membrane-anchored form of MCAM, a soluble form is produced by the shedding of the membrane-associated form, which is secreted by tumours expressing MCAM and has autocrine effects on cancer cell proliferation and survival." (PMID 40713600, 2025). "High expression of both the EC marker KDR/VEGFR2 and the PVC marker CSPG4 showed significant association with poor overall survival (p < 0.05), suggesting that high levels of MCAM gene expression reflect greater vascularisation of tumours and associated poor prognosis." (PMID 37138793, 2023). "Furthermore, gene expression signatures defining invasiveness and a stem cell-like phenotype were most strongly associated with mesenchymal-like tumour cells with low levels of MCAM mRNA, likely to represent a hybrid epithelial/mesenchymal (E/M) state." (PMID 37138793, 2023). "MCAM is a cell adhesion molecule associated with tumor progression." (PMID 36739428, 2023). "The evidence suggested that the MCAM gene may facilitate tumor cell migration and was associated with metastasis and poor prognosis in OS patients." (PMID 34961985, 2022). "Additionally, we identified that MCAM expression was inversely linked to miR-640 expression, and positively linked to circ_0097271 expression in OS tumor samples." (PMID 36340580, 2022). "Based on the gene markers and GSVA, C1_CAFs were found to express tumor angiogenetic and invasion markers [including matrix metalloproteinase 9 and melanoma cell adhesion molecule] that are associated with vascular remodeling, vascular development and vascular diameter size." (PMID 34367994, 2021). "Additionally, MPM patient-derived peripheral blood samples were evaluated for the presence of MCAM-positive CTCs and tumor-associated CECs." (PMID 28577209, 2017). "MCAM has been implicated in several mechanisms critical to tumor cell motility and metastasis, and was identified as a component of a “Wnt-receptor-actin-myosin-polarity (WRAMP)” structure that was linked to polarization and protrusion retraction for WM239a cells." (PMID 24349113, 2013).